ADAM33 (ADAM metallopeptidase domain 33)
Diseases named in the same sentence as ADAM33 in open-access papers (continued):
Sharing a sentence is not in itself a finding about the gene and the disease.
psoriasis (4 papers, 2007 to 2025). An autoimmune condition characterized by red, well-delineated plaques with silvery scales that are usually on the extensor surfaces and scalp. "Test of association of psoriasis and early-onset psoriasis with ADAM33 and PSORS1 SNPs under a general genetic model using the GEE method." (PMID 18560587, 2008). "Further research is needed to further replicate the present association, to assess potential associations in various psoriasis subtypes by studying larger samples and to understand the potential regulation of ADAM33 at the epidermal level." (PMID 18560587, 2008). "This is the first study that replicates an association between genetic variants in ADAM33 and psoriasis." (PMID 18560587, 2008). "No replication study on the association between genetic variations in ADAM33 and psoriasis has been published so far." (PMID 18560587, 2008). "For the first time, an association between ADAM33 and psoriasis initially observed in French families of psoriasis is replicated." (PMID 18560587, 2008). "The rs512625 SNP in ADAM33 was found associated with psoriasis at p = 0.01, the usual threshold required for replication (OR [95% CI] for heterozygotes compared to the reference group of homozygotes for the most frequent allele = 0.61 [0.42;0.89])." (PMID 18560587, 2008). "Association between ADAM33 and psoriasis was then monitored using FBAT when stratifying the families according to the presence or absence of this risk haplotype." (PMID 17878941, 2007). "We attempted to confirm our findings of association between ADAM33 and psoriasis in a broader family sample." (PMID 17878941, 2007). "The identification of ADAM33 as a psoriasis susceptibility gene identified by positional cloning in an outbred population should provide insights into the pathogenesis and natural history of this common disease." (PMID 17878941, 2007). "Beyond its involvement in respiratory conditions, ADAM33 has been implicated in palmar dermatoglyphic patterns and cutaneous disorders such as psoriasis and atopic dermatitis, where polymorphisms consistently associated with early onset forms suggest roles in cell adhesion and epidermal remodeling." (PMID 41373738, 2025). "The independent association of PSORS1 with other genes, such as ADAM33, is coherent with the role of various processes including adaptative and innate immunity, inflammation and remodelling in the occurrence and perpetuation of psoriasis, a complex disease." (PMID 18560587, 2008). "Regarding ADAM33, the rs628977 SNP was more specifically associated with early-onset psoriasis." (PMID 18560587, 2008). "Interestingly, the 2 ADAM33 SNPs associated with psoriasis in the present analysis were part of the 3-SNPs haplotypes showing the strongest associations in the initial study." (PMID 18560587, 2008). "Interestingly, after adjustment on PSORS1 polymorphisms, the association between ADAM33 and psoriasis remained significant." (PMID 18560587, 2008). "As previously observed for HLA-cw6, SNPs in ADAM33 may also be more specifically associated with early-onset psoriasis." (PMID 18560587, 2008). "Recently a genome-wide scan in French extended families of psoriasis confirmed the presence of a psoriasis susceptibility locus on chromosome 20p13, and identified by positional cloning the ADAM33 gene (A Disintegrin And Metalloproteinase 33) as a psoriasis susceptibility gene." (PMID 18560587, 2008). "Association between psoriasis and two genetic variations (rs512625 and rs628977) in ADAM33." (PMID 18560587, 2008). "Thus, the contribution of specific ADAM33 alleles to the familial clustering and individual risk prediction of psoriasis is likely to be relatively small, and these issues of case selection should be addressed in future replication studies." (PMID 17878941, 2007).
psoriasis (continued). "This first report of an association between ADAM33 and psoriasis confirms that common biological pathways may be involved in the etiology of psoriasis and other clinically distinct immune-mediated diseases." (PMID 17878941, 2007). "Thus, the gene ADAM33 was found to be significantly associated with psoriasis in this family set (The best association was on a 3-SNP haplotype P = 0.00004, based on 1,000,000 permutations)." (PMID 17878941, 2007). "Thus, we describe the identification of ADAM33 as being a novel psoriasis susceptibility gene." (PMID 17878941, 2007). "Of interest, in the context of psoriasis, a Th1 disease, is the demonstration of a down regulation of the expression of ADAM33 by IFNG (Interferon-gamma), the prototypical Th1 cytokine, in airway smooth muscle cells." (PMID 18560587, 2008). "Interestingly, rs512625, the ADAM33 SNP showing the strongest association with psoriasis considered as a whole in the present analysis, was also among the SNPs showing the strongest association with psoriasis by single SNP and haplotype analyses in the initial study." (PMID 18560587, 2008). "The importance of this observation should be evaluated by further delineating the biological role of ADAM33 in psoriasis." (PMID 17878941, 2007). "For psoriasis, negative associations for ADAM33 were also retrieved, indicating potential disagreements between studies." (PMID 40110561, 2025). "Our results also suggest that these two ADAM33 SNPs have independent effects on psoriasis." (PMID 18560587, 2008). "Although the number of informative families was reduced, the associations between ADAM33 3-SNPs haplotypes and psoriasis were still observed in the group of patients not carrying HLA-Cw6, indicating that the 2 loci act independently." (PMID 17878941, 2007). "This suggests independent effects of ADAM33 and PSORS1 on psoriasis." (PMID 18560587, 2008).
airway hyperresponsiveness (3 papers, 2019 to 2025). "These linked variants have previously been associated with altered expression of ADAM33 in bronchial epithelium and with downstream phenotypes such as airway hyperresponsiveness, extracellular matrix deposition, tissue remodeling, and pro-inflammatory signaling." (PMID 41373738, 2025). "Variants in a disintegrin and metalloprotease 33 (ADAM33) and protocadherin-1 (PCDH1) were reported to be involved in airway hyperresponsiveness and airway remodeling." (PMID 30906771, 2019).
childhood asthma (3 papers, 2006 to 2017). "The results showed that the ADAM33 rs2280091 polymorphism in all four genetic models was associated with an increased risk of childhood asthma." (PMID 28876365, 2017). "ADAM33, the first asthma candidate gene identified by positional cloning, may be associated with childhood asthma, lung function decline and bronchial hyperresponsiveness." (PMID 16784537, 2006). "This study aimed to investigate the association between ADAM metallopeptidase domain 33 (ADAM33) gene polymorphisms and the risk of childhood asthma." (PMID 28876365, 2017). "The TT-genotype of ADAM33 rs511898 (p = 0.03), the CG/GG-genotype of ADAM33 rs528557 (p = 0.08) and the TT-genotype of ORMDL3/GSDMB rs7216389 (p = 0.08) were negatively associated with childhood asthma." (PMID 25768087, 2015). "In the ADEM study, the minor alleles of ADAM33 rs511898 and rs528557 and the ORMDL3/GSDMB rs7216389 polymorphisms were negatively associated, whereas the minor alleles of IL4 rs2243250 and rs2070874 polymorphisms were positively associated with childhood asthma." (PMID 25768087, 2015). "Very large studies investigating childhood asthma by Lind and Raby could not find any association between single ADAM33 SNPs or haplotypes and childhood asthma." (PMID 16784537, 2006).
keloid (3 papers, 2016 to 2024). An irregularly shaped, elevated mark on the skin caused by deposits of excessive amounts of collagen during wound healing. "ADAM33 is a member of ADAM family that is associated with keloid scars in the northeastern Chinese population." (PMID 28101509, 2016). "Subsequently, a case-control study suggested that keloid development may be associated with the ADAM33 single-nucleotide polymorphisms, comparing blood test results of 283 subjects with keloids and 290 controls." (PMID 38476235, 2024). "In addition, the factors related to Th1, Th2, and Th17 cells such as IL4/IL13, IL17A/IL22, ADAM33, IFN-γwere upregulated overall in keloid and AD." (PMID 38476235, 2024).
lung disease (3 papers, 2013 to 2025). "Our findings highlight the importance of ADAM33 as a pleiotropic gene involved not only in pulmonary disease, but in cardiovascular disease as well." (PMID 23861802, 2013). "So far, ADAM33 has been related to pulmonary diseases and lung function decline." (PMID 23861802, 2013). "On the other hand, ADAM33 interacts with CTSK and CTSV genes, phagosomal cathepsin genes, being related to lung diseases." (PMID 36411793, 2022). "Although ADAM33 is not located on a sex chromosome, sex-related differences in lung disease presentation and progression cannot be completely excluded." (PMID 41373738, 2025).
allergic respiratory disease (2 papers, 2016 to 2018). A respiratory system disease with a basis in a pathological type I hypersensitivity reaction. "Even though this functional link between ADAM33 and allergic airway inflammation, its role in the pathophysiology of allergic respiratory diseases is still to be clarified." (PMID 27624002, 2016).
eczema (2 papers, 2016 to 2023). "Wheezing and eczema comorbidity was also associated with another ADAM33 variant (rs543749, z = 3.259, p = 1.16*10−3) in high LD with rs3918396 (r2 = 66%)." (PMID 27624002, 2016). "Individuals with ADAM33 rs3918396 A allele have an increased risk to present wheezing and eczema comorbidity with respect to carriers of GG genotype (16% vs. 7%, respectively)." (PMID 27624002, 2016). "We also observed that other ADAM33 variants (rs3918396 and rs543749) are associated with wheezing and eczema comorbidity." (PMID 27624002, 2016). "Due to its association with wheezing and eczema comorbidity, ADAM33 may also be involved in the atopic march." (PMID 27624002, 2016). "Our genetic results indicated that ADAM33 might be involved in the molecular processes associated with the comorbidity of wheezing and eczema." (PMID 27624002, 2016). "The second strongest PWS result was observed between ADAM33 rs3918396 and the wheezing and eczema comorbidity (z = 3.60; p = 3.41*10−4)." (PMID 27624002, 2016).
gastric cancer (2 papers, 2017 to 2023). A primary or metastatic malignant neoplasm involving the stomach. "It has been reported that VEGF-D-enhanced ADAM33 plays an important role in tumor cell proliferation in the gastric cancer cell line SNU-601." (PMID 28056993, 2017).
bronchitis (1 paper, 2017). An acute or chronic inflammatory process affecting the bronchi. "Significant differences in the prevalence and risk of bronchitis were found in genotypes of LT-α and TNF-α, but not in ALOX5, LTC4S, TBXA2R, ADAM33, NOS1 and ORMDL3 in the Inuit populations residing both in Greenland and in Denmark." (PMID 28740106, 2017).
cardiac hypertrophy (1 paper, 2013). "Moreover ADAM12, a member of the same subfamily and closely related to ADAM33, is involved in development of cardiac hypertrophy that leads to sudden cardiac death." (PMID 23861802, 2013).
COVID-19 (1 paper, 2023). A disease caused by infection with severe acute respiratory syndrome coronavirus 2. "This research evaluated the association of the polymorphisms rs16969968 (CHRNA5) and rs3918396 (ADAM33) in patients who developed severe COVID-19." (PMID 37372959, 2023). "Genotype and allele analysis was made comparing smokers vs. non-smokers patients; the codominant model shows that does not exist an association between rs16969968 (CHRNA5) and rs3918396 (ADAM33) and COVID-19." (PMID 37372959, 2023). "This research aims to evaluate the association of the polymorphisms rs16969968 (CHRNA5) and rs3918396 (ADAM33) in patients who developed severe COVID-19." (PMID 37372959, 2023).
emphysema (1 paper, 2014). "We found that T2, T1 and Q-1 were associated with decreased TLCO of COPD, suggesting that the ADAM33 also play a role in the pathogenesis of emphysema." (PMID 25369941, 2014).
invasive lobular carcinoma (1 paper, 2009). "Further studies are also needed to determine the prognostic and predictive significance of ADAM33 methylation and silencing in invasive lobular carcinoma." (PMID 19267929, 2009). "In summary, our findings suggest that ADAM33 is a novel tumour suppressor gene that may be useful as a molecular marker for invasive lobular carcinoma of the breast." (PMID 19267929, 2009).
nicotine addiction (1 paper, 2023). "Several genes are associated with nicotine addiction, such as CHRNA5 and ADAM33." (PMID 37372959, 2023).
Obesity (1 paper, 2015). Accumulation of substantial excess body fat. "In conclusion, in patients with obesity and type 2 diabetes, insulin infusion leads to a suppression of the expression of IL-4, ADAM-33, LIGHT, and LTBR in parallel with a reduction in plasma NOM, TGFβ, MCP-1, and MMP-9 concentrations." (PMID 25642424, 2015).
papillary thyroid cancer (1 paper, 2023). "The results of cell counting kit-8 and colony formation assays showed that ectopic ADAM33-n in papillary thyroid cancer cell lines restricted cell proliferation and colony formation." (PMID 36977901, 2023). "To this end, we intended to determine the effect of ectopic ADAM33 on papillary thyroid cancer cell lines and, for the first time, report the downregulated ADAM33 expression levels in thyroid cancer." (PMID 36977901, 2023).
retinoblastoma (1 paper, 2025). A malignant tumor that originates in the nuclear layer of the retina. "Moreover, genome-wide methylation profiling of aqueous humor cfDNA has defined robust subtypes of retinoblastoma linked to clinical outcomes, identifying differentially methylated genes (e.g., TFF1, BCHE, PCDHB2, ADAM33) that correlate with aggressive disease and chemoresistance." (PMID 41150792, 2025).
sensitization (1 paper, 2014). "SNPs in or near JAK2, CNOT6, MAML1, CD40, IL-4R, and IL-5RA genes were associated with allergic sensitization and SNPs in or near JAK1, JAK3, IL5RA, FCER1A, and ADAM33 genes were associated with cockroach sensitization." (PMID 25505553, 2014).
thyroid cancer (1 paper, 2023). "We quantified the ADAM33-n expression level in the collected thyroid cancer biopsies and found that the aberration of ADAM33 in tumors is primarily attributable to the downregulation of ADAM33-n." (PMID 36977901, 2023). "Taken together, our findings demonstrate that ADAM33 possesses oncogenic function in thyroid cancer cells in vitro." (PMID 36977901, 2023). "Altogether, our study findings present a potential explanatory model of how the downregulation of the oncogenic gene ADAM33 promotes the pathogenesis of thyroid cancer." (PMID 36977901, 2023). "After determining its expression in the collected thyroid cancer biopsies, we observed that ADAM33-n was downregulated in tumors compared with the normal controls." (PMID 36977901, 2023). "A contradiction exists between ADAM33 downregulation in thyroid cancer biopsy samples and its oncogenic function in thyroid cancer cells, and its underlying mechanism remains unelucidated." (PMID 36977901, 2023). "Altogether, our study findings demonstrate how the downregulation of an oncogenic gene, ADAM33, promotes the pathogenesis of thyroid cancer, thereby indicating its potential as a therapeutic target." (PMID 36977901, 2023). "In our study, the real-time PCR results of 139 thyroid cancer biopsy samples support that ADAM33 is downregulated in tumor tissues." (PMID 36977901, 2023). "The findings of our study provide information on the mechanism by which the oncogene ADAM33 contributes to the pathogenesis of thyroid cancer." (PMID 36977901, 2023). "Considering the aberrant ADAM33 expression in thyroid cancer, we stably overexpressed its coding sequences in two PTC cell lines (MDA-T32 and BCPAP) using a doxycycline-inducible lentivector." (PMID 36977901, 2023). "In summary, we found that ADAM33-n, an N-terminal isoform of ADAM33, is the dominant contributor to ADAM33 aberration in thyroid cancer." (PMID 36977901, 2023). "The results showed that ADAM33 expression in thyroid cancer was substantially decreased compared with that in the two normal controls." (PMID 36977901, 2023). "To explore the role of ADAM33-n in the pathogenesis of thyroid cancer, we stably transfected the coding sequences of ADAM33-n in MDA-T32 and BCPAP cells using a doxycycline-inducible lentivector." (PMID 36977901, 2023). "Therefore, we focused on the role of the transcript ENST00000617732 in thyroid cancer; this transcript was named ADAM33-n based on its amino acid sequences." (PMID 36977901, 2023). "Therefore, we concluded that ADAM33-n acts as a tumor suppressor by blocking the oncogenic role of full-length ADAM33 in thyroid cancer." (PMID 36977901, 2023). "In the present study, we aimed to investigate the function of ADAM33 in thyroid cancer." (PMID 36977901, 2023). "Collectively, our findings demonstrate that ADAM33 RNA level is decreased in thyroid cancer." (PMID 36977901, 2023). "As the chaperon-like prodomain of ADAM33 binds to the catalytic domain to inhibit its proteolytic activity, we hypothesized that ADAM33-n is a natural inhibitor of full-length ADAM33 and that the downregulation of ADAM33-n consequently restores the oncogenic function of ADAM33 in thyroid cancer." (PMID 36977901, 2023). "Collectively, our data demonstrated that, unlike full-length ADAM33, ADAM33-n is a tumor suppressor in thyroid cancer cells in vitro." (PMID 36977901, 2023).